LRP6 (LDL receptor related protein 6)
Diseases named in the same sentence as LRP6 in open-access papers (continued):
Sharing a sentence is not in itself a finding about the gene and the disease.
tumor (continued). "For instance, antibody against LRP6 was able to inhibit tumor growth." (PMID 30411539, 2018). "The LRP6 antagonist Mesd markedly suppressed tumor growth in MMTV-Wnt1 xenograft models." (PMID 29444668, 2018). "This hypothesis was confirmed in vivo in a xenograft model in which the depletion of LRP5 or LRP6 delayed tumor growth." (PMID 29854300, 2018). "However, the depletion of LRP5 had a similar effect to that of LRP6 on tumor growth in a xenograft model." (PMID 29854300, 2018). "(B) Upregulation of CCN2 and LRP6 in Oxaliplatin-treated subcutaneous tumor tissues." (PMID 28870205, 2017). "Overexpression or activation of LRP6 could activate Wnt signaling and promote tumor cell migration in vitro." (PMID 29312635, 2017). "They showed that either knockdown of LRP6 or LRP6 antagonist suppressed tumor growth." (PMID 22570728, 2012). "In addition, it has been demonstrated that specific LRP6 antibodies were able to block MMTV-Wnt1 or MMTV-Wnt3 xenografts in vivo, and that recombinant Mesd protein, an LRP6 antagonist, markedly suppressed tumor growth in MMTV-Wnt1 xenograft models." (PMID 22195040, 2011). "We next determined whether the LRP6 antibodies could antagonize or potentiate endogenous, or autocrine, Wnt signaling detected in a variety of tumor cell lines." (PMID 20856934, 2010). "Here, we found that LRP6 was associated with the expression of a variety of m6A modification-related molecules, and further confirmation is needed as to whether LRP6 can influence tumor progression by regulating the expression of m6A modification-related genes." (PMID 38226972, 2024). "A number of the identified tumour-associated antigens are known to signal via this cascade, HMGN5, TFG, MAEL, SOX15 and Dicckopf-1, the latter of which has been investigated in numerous other biomarker signatures and like TFG interacts via the Wnt co-receptor LRP6." (PMID 34728792, 2022). "Importantly, when the WNT2/LRP5/LRP6 canonical Wnt signature was used for analysis using STAD tumor data, the modest correlation with TAMs (compare lines 2b, 6b) and M2 markers (compare lines 4b, 8b) was lost, favoring a role for the non-canonical Wnt pathway in macrophage infiltration." (PMID 33869179, 2021). "Importantly, circ-LRP6 depletion significantly retarded tumor growth in vivo." (PMID 32867570, 2020). "Furthermore, we found that the co-expression of LRP6 could prolong the survival of tumor-bearing mice in vivo, which suggests its potential to develop a promising strategy for clinical treatment of cancer in the future." (PMID 33042788, 2020). "Through our research, this anti-tumor effect of LMWH in this study may be contributed to the interfering core regulatory functions of CCN2 proteins that function to orchestrate the Wnt co-receptor LRP6." (PMID 28870205, 2017). "WNT7A-FZD6/FZD3+LRP6/LRP5, critical components of the canonical Wnt signaling pathway, were exclusively expressed in STAR + cells and tumor cells." (PMID 40098624, 2025). "Secreted WNT5A was suggested to interact with a wide range of tumor cell-expressing receptors, such as LRP5, LRP6, FZD5, and FZD6." (PMID 40524253, 2025). "An FDA-approved antiparasitic drug Niclosamide, suppresses tumor growth and metastasis by targeting FZD1, DVL2, and LRP6 with minimal animal toxicity." (PMID 41516083, 2025). "Knockdown of LRP6 reduced cell proliferation, and its expression was positively correlated with the oncogene FGF8, suggesting a role in tumor progression." (PMID 40943055, 2025). "Utilizing a published scRNA-seq dataset comprising 15 tumor samples and one nasopharynx, UMAP visualization revealed that SOX2, NTRK2, LRP6, and PTPRZ1 from our candidate list were predominantly expressed in epithelial and malignant patient cells." (PMID 40133476, 2025). "In ESCC, circ-SLC7A5, circ-LRP6 and circ-TTC17 have been reported to play tumor-promoting roles, but circFoxo3 and circSMAD7 act tumor-inhibiting roles." (PMID 38514579, 2024).
tumor (continued). "In TNBC, the Wnt signaling pathway is hyper-activated and promotes tumor progression through the overexpression of Frizzled and its co-receptors, LDL Receptor-Related Protein 5 (LRP5) and LDL Receptor-Related Protein 6 (LRP6)." (PMID 39201539, 2024). "The acetylation of LRP6 stimulates the activity of LRP6 and the self-renewal of CD110 colon tumor initiating cells." (PMID 37164974, 2023). "Increased LRP6 phosphorylation involved in nuclear accumulation of β-catenin also has been observed in CRC, with relevance for tumor malignancy and staging, along with poor prognosis." (PMID 36983771, 2023). "Similarly, a recent study reported single‐domain antibody fragments binding to LRP6 strongly inhibited the growth of Wnt‐hypersensitive intestinal stem cells through stem cell exhaustion and promoting terminal differentiation provides a promising strategy for treating Wnt‐hypersensitive tumours." (PMID 34997691, 2022). "Simvastatin treatment significantly inhibited transcript levels of LRP6 (1.69‐fold), AXIN2 (3.33‐fold) and Cyclin D1 (1.59‐fold), while we found a higher expression of the tumour suppressor APC levels compared to control." (PMID 35118811, 2022). "Consistent with the observed increase in WNT related genes in tumor cells, we saw high scores for WNT-related interactions (ligands Sfrp1 and Wnt5a and receptors Fzd6, Fzd7 and Lrp6) and significant BMP-related interactions (e.g. from Bmp4 with Bmpr1a)." (PMID 35600339, 2022). "Several studies have shown that miR-126 targets include ADAM9, LRP6, PIK3R2, CXCR4, and SLC7A5, all of which participate in the development of diverse tumor types." (PMID 32554852, 2020). "Another strategy of tumor targeting was used with the NT4 peptide, a tetrabranched peptide from the human neurotensin, capable of binding LRP1 and LRP6 by mimicking ApoE and midkine heparin binding site." (PMID 32850302, 2020). "Another way in which the miR-34 family contributes to tumour suppressive function is that miR-34a, miR-34b*, and miR-34c-5p inhibit the Wnt pathway by repression of Wnt ligand co-receptors (WNT1/3; LRP6), with HMG-box transcription factor (LEF1) and β-catenin." (PMID 31658284, 2019). "We next examined the tumor formation and Wnt activity following siRNA knockdown of LRP5, LRP6, and β-catenin." (PMID 31881970, 2019). "Accordingly, ectopic expression of a constitutively activated form of LRP6 in HCC cells promotes proliferation, invasion and migration, and increases tumour formation in immunodeficient mice." (PMID 31412666, 2019). "Aside from these observations, reduced expression of the LRP6 antagonist DKK1 has also been observed in CRC patients, and is inversely correlated with tumour grade and metastatic potential." (PMID 31412666, 2019). "For example, KRAS induces the phosphorylation of the Frizzled co-receptor LRP6, leading to a cascade of events that promotes activation of the WNT pathway and increases in cell migration and tumor growth." (PMID 31623618, 2019). "Further, the molecular expression of lipoprotein receptor related protein 6 (LRP6) and β-catenin were down-regulated in rottlerin-treated ACC cells, which indicated that Wnt/β-catenin signaling was involved in the tumour-suppressive function of rottlerin." (PMID 28423559, 2017). "Among R-Spondins (RSPO) ligands family, RSPO2 binding to Lgr5 regulates receptor turnover through stabilization of tumor suppressors ZNFR3 and RNF43 membrane E3 ligases, that mediate ubiquitination and consequent degradation of LRP6/5 receptors." (PMID 29354056, 2017). "In the present study, increased expression levels of CCN2 and LRP6 were proved in oxaliplatin-resistant HCC cell lines and subcutaneous tumor tissues." (PMID 28870205, 2017). "The alterations of CCN2 and LRP6 expression levels were further validated using IHC staining in tissue microarrays (TMA) containing tumor and non-tumor tissues from 374 HCC patients (validation cohorts)." (PMID 28870205, 2017).
tumor (continued). "As a result, colocalization with LRP6 is observed during PAR2 induction and initiation of large tumor formation, in vivo." (PMID 28418856, 2017). "As compared with non-tumor liver tissues, up-regulation of CCN2 and LRP6 was observed in 68.75% (66/96) and 76.04% (73/96) HCC samples, respectively." (PMID 28870205, 2017). "To determine the role of CCN2 and LRP6 in HCCs, we first detected the mRNA expression levels of CCN2 and LRP6 in 96-paired HCC and adjacent non-tumor liver tissues." (PMID 28870205, 2017). "PEDF receptors (ATP5B, PNPLA2, and LRP6) and CD47 mRNA and protein expression were quantified in macrophages and tumor cells by quantitative RT-PCR, western blot, immunofluorescence and flow cytometry." (PMID 28403150, 2017). "Among them, LRP6 expression was found to be upregulated in OSCC tissues, and correlated with a cluster of clinicopathologic parameters, including smoking, drinking, tumor differentiation status, lymph node metastasis and survival time." (PMID 28880263, 2017). "NT4 selectively targets tumor cells by binding to membrane sulfated glycosaminoglycans (GAG) and to endocytic receptors, like LRP1 and LRP6, which are established tumor markers." (PMID 26626158, 2015). "Transcriptional knockdown of LRP6 in TNBC MDA-MB-231 cells significantly decreased Wnt/β-catenin signaling, cell proliferation, and tumor growth in vivo." (PMID 22195040, 2011). "They found that under conditions of reduced LRP5/LRP6, Wnt5a strongly activates the non-canonical pathway, leading to elevated p-c-jun and promoting tumor cell metastasis." (PMID 38706907, 2024). "Using data from the TCGA database we investigated the relationship between LRP6 and tumor TMB and MSI, and found that LRP6 expression was significantly positively correlated with tumor TMB in LUSC, TGCT, GBM, READ, and KICH, and significantly negatively correlated with tumor TMB in DLBC, UCS, etc.." (PMID 38226972, 2024). "Moreover, the protein levels of LRP5, LRP6, TCF-4, and LEF1 in the tumor were also significantly down-regulated by AR decoction or oxaliplatin treatment in xenograft mice." (PMID 34991661, 2022). "For example, pharmacological blockade of WNT signaling with LGK974, which inhibits WNT ligand secretion through the acyltransferase porcupine, or with an antibody against the WNT receptor LRP6 leads to a reduction in the number of DTP cells and a delay of tumor relapse upon drug withdrawal." (PMID 36048538, 2022). "Considering these results collectively, we postulate that Lrp5 but not Lrp6 in osteocytes can enhance tumor suppression." (PMID 34230453, 2021). "Collectively, these results indicated that Lrp5 but not Lrp6 altered the tumor-suppressive capability of osteocytes." (PMID 34230453, 2021). "Our recent studies showed that tumor-promoting phorbol ester TPA could stabilize CK1ε, enhance its kinase activity, induce LRP6 phosphorylation at Thr1479 and Ser1490, finally leading to activation of the Wnt/β-catenin pathway." (PMID 34615853, 2021). "Forced expression of LRP6 without its 3’-UTR restored these protein expression levels regulated by miR-137 in tumor tissues." (PMID 33718112, 2020). "Overall, these studies clearly indicate that LRP6 may represent a promising therapeutic target for CRC, in particular for WNT-hypersensitive tumours." (PMID 31412666, 2019). "Hence, by targeting LRP6 expression, vitamin D analogs act as therapeutic WNT inhibitors to inhibit PDAC tumor growth." (PMID 31412666, 2019). "Furthermore, a bispecific antibody (GSK3178022) to LRP6 that is capable of blocking stimulation by a range of WNT and R-spondin (RSPO) ligands in vitro potently delayed tumor growth in a patient-derived RSPO fusion model of CRC." (PMID 31412666, 2019). "In this study, we provide a series of experimental evidences that VSTM2A is a critical tumor suppressor in CRC and a novel antagonist of Wnt signaling by direct binding to Wnt co-receptor LRP6, suppressing LRP6 activation and inducing its endocytosis and degradation." (PMID 31588233, 2019).
tumor (continued). "LRP6 is overexpressed in TNBC, favoring cell proliferation, migration, invasion and tumor growth." (PMID 29854300, 2018). "Additionally, in tumor tissues collected from A549 xenograft model, ART and its derivatives effectively reduced Wnt5-a/b, LRP6, and Dvl2 but significantly increased both NKD2 and Axin2 (p < 0.001)." (PMID 27119499, 2016). "Both LRP6 and TBL1X are found to function as oncogenes during tumor progression." (PMID 25491321, 2014). "Furthermore, no obvious reduction in mammary hyperplasia was observed, and tumor onset was only slightly delayed in adult MMTV-Wnt1;Lrp6+/− females (p = 0.08)." (PMID 19503830, 2009). "While detailed studies on LRP6 in NETs are lacking, findings from other cancers suggest that LRP6 overexpression may contribute to tumor aggressiveness." (PMID 39796676, 2024). "LRP6 is a co-receptor in the WNT signalling pathway that supports the proliferation of tumour cells, and several lines of evidence have shown that inhibition of LRP6 leads to suppression of tumour cell proliferation and enhances chemosensitivity of cancer cells." (PMID 37198490, 2023). "Further analysis showed that LRP5 and LRP6 membrane receptors presented lower expressions in tumor cells of the model + sh-SOST group than that of the model + sh-NC group, demonstrating that SOST suppression could decrease the expressions of LRP5 and LRP6." (PMID 35785219, 2022). "Unexpectedly, the absence of LRP6 did not significantly affect tumor development in ApcMin/+ mice." (PMID 34359960, 2021). "It has been reported that Dkk3 might orchestrate concomitant activation of β-catenin and YAP/TAZ in cancer-associated fibroblasts (CAFs) by interfering with the Kremen negative regulator and increasing cell-surface levels of LRP6 as an HSF1 effector, required to promote tumor aggressiveness." (PMID 33425757, 2020). "However, no apparent correlation was observed between LRP6 expression and patient gender, age, tumor size, tumor location or clinical stage." (PMID 28880263, 2017). "Likewise, epithelial Lrp6 deletion does not affect intestinal tumor load and size in ApcMin/+ mice." (PMID 34359960, 2021). "When we compared anti‐LRP6 alone with the anti‐LRP6/DKK1 combination strategy, again there was variation in each treatment group, however FACS analysis revealed no changes in tumor burden." (PMID 36987921, 2023). "Of note, the correlation between the WNT2/LRP5/LRP6 signature and the mesenchymal signature was decreased when using STAD tumor data, compared to the non-canonical signatures." (PMID 33869179, 2021). "Vessel-specific LRP6 expression in tumors supports the idea that DKK1 and DKK2 expression does not affect tumor cell proliferation." (PMID 24091497, 2014). "The association analyses between NHERF1 and the other markers revealed a positive direct relation between cNHERF1 and FZD4, LRP5, LRP6, and TCF1 expression, but not with β-catenin, suggesting a possible novel tumor progression mechanism, that involves Wnt signaling components." (PMID 31336689, 2019). "Thus, targeting specific regions of LRP6 ectodomain, especially the P3E3P4E4 region, may represent a promising strategy to reduce β-catenin-dependent signaling in tumours, without altering other WNT functions." (PMID 31412666, 2019). "Co-receptor LRP5 and LRP6 could interplay between themselves and attach to FZD and Wnt ligands, prohibiting FZD mediated canonical and non-canonical pathways and further regulating tumor metastasis." (PMID 29108281, 2017).
cancer (102 papers, 2011 to 2025). A tumor composed of atypical neoplastic, often pleomorphic cells that invade other tissues. "LRP6, linked to several cancer progressions including human triple-negative breast cancer, NSC, and others, shares structural similarities with LRP5." (PMID 38534454, 2024). "CKAP4 and LRP6 have been reported to be direct DKK1 receptors implicated in cancer cell proliferation, with similar affinities but distinct cysteine-rich domains." (PMID 38529014, 2024). "Deregulation of the Wnt signalling family members, including LRP6, has been reported to alter Wnt signalling activity and then lead to induction of cancer-associated genes as well as abnormal cell proliferation." (PMID 35052459, 2022). "In humans, some LRP6 single-nucleotide polymorphisms (SNPs) and mutations in the LRP6 gene have been associated with increased or decreased risk of cancer development." (PMID 36012187, 2022). "From these previous studies, it is evidently showed that mutations in LRP6 have been linked to a wide variety of cancers." (PMID 31031810, 2019). "As we were unable to perform a complete cosegregation analysis in this family, or in any of the other PTPN12 or LRP6 families, it remains to be established to what extend carriers of variants in these genes tend to develop cancer at a young age." (PMID 26901136, 2016). "Thus, LRP6 is being investigated as a biological indicator for assessment of the risk of some cancer types." (PMID 35052459, 2022). "Interestingly, the metastatic cancer cells acquired additional mutations in Wnt pathway components (APC mutations or amplifications of LRP6 and WNT2B), underlining the importance of Wnt signaling for metastasis." (PMID 35327645, 2022). "LRP6 is also involved in regulating the activity of cancer-associated fibroblasts (CAFs)." (PMID 34589484, 2021). "Additionally, some polymorphisms identified in the LRP6 gene have been associated with different susceptibility to the development of cancers." (PMID 31412666, 2019). "Therefore, further investigations are in need to validate the currently reported biomarkers in LRP6, 7, and 8 especially in unmasking the underlying mechanism of these proteins in regulating cancer progression through Wnt/β-catenin pathway." (PMID 31031810, 2019). "However, activation of LRP6-Wnt-β-catenin signalling is also implicated in the development of various cancers." (PMID 26919115, 2016). "Hence, it will be relevant to determine whether inhibiting LRP6 function interferes with tumoral properties of human KRAS-mutated cancer cells." (PMID 31412666, 2019). "Subsequently, we also explored the correlation between the expression levels of LRP6 and the expression levels of common immune checkpoints in 33 cancers, such as SIGLEC15, IDO1, CD274, HAVCR2, PDCD1, CTLA4, LAG3 and PDCD1LG2." (PMID 38226972, 2024). "Blocking Wnt signaling through LRP6 decreased cancer cell self-renewal ability and seed tumors in vivo." (PMID 38534454, 2024). "LRP6, a member of the low-density lipoprotein receptor family, has been widely recognized for its pivotal role in driving cancer progression via aberrant upregulation 31,32." (PMID 38250152, 2024). "Further studies are needed to elucidate the function of LRP6 in cancer and characterize its potential as a therapeutic target." (PMID 36983771, 2023). "LRP6 overexpression, observed in many types of cancer and malignant tissues, leads to an abnormal Wnt pathway that is linked to tumorigenesis." (PMID 36012187, 2022). "GRP94 is a master ER chaperone that plays a role in protein quality control in response to stress, inflammation, and cancer through its client protein networks, such as LRP6-Wnt, GARP-TGF-β signaling pathways, etc.." (PMID 33898309, 2021). "In HCC with HBx truncated at C-terminus (HBxΔC), Cav-1 was upregulated at the transcriptional level, thereby promoting cancer aggressiveness via the LRP6/β-catenin/FRMD5 signaling axis." (PMID 34168559, 2021).